HMGB1 (high mobility group box 1)
Diseases named in the same sentence as HMGB1 in open-access papers (continued):
Sharing a sentence is not in itself a finding about the gene and the disease.
Sepsis (continued). "Deletion of the HMGB1 gene or neutralizing circulation of HMGB1 has been shown to have a protective effect against fatal endotoxemia and sepsis." (PMID 36189354, 2022). "We mainly focused on HMGB1, which directly impaired the myocardial function in sepsis, and the expression of HMGB1 was remarkably increased in the CLP model." (PMID 35656291, 2022). "HMGB1 plays a pivotal role in the progression of sepsis, which can deliver extracellular LPS into the cytosol of macrophages and endothelial cells to mediate CASP11-dependent pyroptosis and lethality in sepsis." (PMID 36250055, 2022). "proved that the activity of bone marrow-derived macrophages in sepsis mice was inhibited after treatment with HMGB1, leading to the increased release of IL-1β and IL-18 through caspase-11-dependent pyroptosis." (PMID 35572571, 2022). "Murine studies demonstrated that endotoxin uses both TLR4 and caspase-11/gasdermin D (GsdmD) pathways to induce the release of HMGB1 from hepatocytes—the major source of circulating HMGB1 in sepsis." (PMID 35160068, 2022). "Vice versa, targeting DAMPs, such as HMGB1 and HPSs, with specific blockers can play a vital role in treating inflammatory diseases, such as sepsis, ischemia, myocardial infarction, etc.." (PMID 35563721, 2022). "In the case of the UPS cargos whose excessive release provokes pathologies, such as IL-1β in diabetes and AD, α-synuclein in PD, and HMGB1 in sepsis, downregulation of their releases would be beneficial for disease control." (PMID 35774225, 2022). "Animal studies have found that HMGB1 triggered systemic inflammatory diseases, including mastitis, sepsis, arthritis, epileptogenesis, necrotizing enterocolitis, acute lung injury, traumatic brain injury, and liver injury." (PMID 35335612, 2022). "The expression of iNOS, COX-2, TNF-α, IL-6, and HMGB-1 is inhibited following phlorotannin treatment in a lipopolysaccharide-induced sepsis model." (PMID 35597942, 2022). "In vivo reduction of lactate production and/or inhibition of GPR81-mediated signaling decreases circulating exosomal HMGB1 levels and improves survival outcome in polymicrobial sepsis." (PMID 34363018, 2022). "calycosin alleviates sepsis-induced ALI in young rats by inhibiting the HMGB1/MyD88/NF-κB pathway and NLRP3 inflammasome activation." (PMID 35720285, 2022). "HMGB1 has already been identified as a therapeutic target in sepsis, and several agents that improve survival in sepsis or endotoxemia work by inhibiting secretion of HMGB1." (PMID 35596191, 2022). "sesamin improves the 7-day survival rate of septic mice, suppresses the inflammatory response in sepsis through the HMGB-1/TLR4/IL-33 signaling pathway." (PMID 35720285, 2022). "In summary, the available data strongly indicate that progression from acute respiratory failure to sepsis in COVID-19 does correlate with the release of HMGB1 (and refs. therein)." (PMID 35454134, 2022). "As HMGB1 maintains and prolongs the pathological process of sepsis, different studies have focused on describing the role of this protein in this condition." (PMID 36016387, 2022). "Another oxidized protein that has been described in neuroinflammation and manifested pathologies is HMGB1, i.e., depression due to neuroinflammation, angiogenesis in cancer and sepsis." (PMID 35740078, 2022). "A late release of HMGB1 in sepsis suggests the existence of a wide therapeutic window for treating sepsis." (PMID 35454134, 2022). "andrographolide inhibits HMGB1-induced inflammatory responses in human umbilical vein endothelial cells and in murine polymicrobial sepsis." (PMID 35720285, 2022). "Disulfide HMGB1 inhibited the release of inflammatory cytokines in sepsis by binding to haptoglobin to induce heme oxygenase-1 (HO-1) and IL-10 production in a CD163+ dependent manner." (PMID 35250993, 2022). "The result indicated that miR-129-5p protected against sepsis-induced ALI by decreasing HMGB1 expression." (PMID 35720285, 2022).
Sepsis (continued). "The role of HMGB1 has been demonstrated in the pathogenesis of sepsis and septic shock; it acts as a key “late-phase” inflammatory mediator." (PMID 36078108, 2022). "Previous studies have shown that HMGB1 plays a role in sepsis, atherosclerosis, rheumatoid arthritis and other inflammation-related diseases." (PMID 35354479, 2022). "Compared with CD19hiFcγRIIbhi B cells from wild-type mice, CD19hiFcγRIIbhi B cells from Hmgb1(C106A) mice significantly reduced the survival of mice with sepsis." (PMID 35983056, 2022). "In short, HMGs, especially HMGA1 and HMGB1, are widely studied and demonstrated to be involved in the occurrence and development of sepsis." (PMID 35720285, 2022). "quercetin exertes protective effects on a rat model of sepsis via inhibition of reactive oxygen species (ROS) and downregulation of HMGB1 protein expression." (PMID 35720285, 2022). "Several damage-associated molecular pattern (DAMP) molecules such as cell-free chromatin, high mobility group protein 1 (HMGB1) and S100 proteins have also been implicated in hyper-inflammation and sepsis pathology." (PMID 35945238, 2022). "Increasing evidence indicates that as a multi-functional mediator, HMGB1 contributes to a variety of systemic diseases, including ischemia-reperfusion injury, enterocolitis, sepsis, and liver injury, indicating the potential of HMGB1 as a therapeutic target." (PMID 35335612, 2022). "magnesium sulfate ameliorates sepsis-induced diaphragm dysfunction in rats via inhibiting HMGB1/TLR4/NF-κB pathway." (PMID 35720285, 2022). "The present study demonstrated a novel role of lactate in HMGB1 lactylation and acetylation in macrophages during polymicrobial sepsis." (PMID 34363018, 2022). "glucan phosphate attenuates myocardial HMGB1 translocation in severe sepsis through inhibiting NF-κB activation." (PMID 35720285, 2022). "In recent years, more novel sepsis biomarkers, such as HMGB-1, CD64, IL-6, heparin-binding protein (HBP) and triggering receptors expressed on myeloid cells-1 (TREM-1), have been identified." (PMID 36411279, 2022). "miR129-5p attenuated LPS-induced podocyte apoptosis, inflammation, and acute kidney injury (AKI) through HMGB1, and plays a protective role in sepsis models in vivo and in vitro." (PMID 35720285, 2022). "In recent years, it has been reported that inhibiting HMGB1 can improve inflammation and advance the prognosis of patients with sepsis." (PMID 36072408, 2022). "These considerations suggest the potential of mitigating inflammatory injury in sepsis and endotoxemia by inhibiting HMGB1 and enzymes involved in aerobic glycolysis." (PMID 35596191, 2022). "Together, these data demonstrate that sepsis increases serum exosomal HMGB1 levels and that lactate exerts a regulatory role in the exosome-mediated release of HMGB1." (PMID 34363018, 2022). "Glycyrrhizin (GL), a natural triterpene glycoside derived from licorice, which protected rats from sepsis by blocking HMGB1 signaling." (PMID 35720285, 2022). "Extracellular HMGB1, a mediator of late sepsis, acts as a major mediator in both acute and chronic inflammation." (PMID 36081910, 2022). "Targeting HMGB1 therapy has been extensively studied in sepsis, ischemia-perfusion injury, organ transplantation, and tumors." (PMID 35250993, 2022). "Clinical evidence has revealed that the levels of circulating HMGB1 are markedly elevated and positively correlated with sepsis severity and mortality." (PMID 34363018, 2022). "Recently, under the worldwide threat of sudden acute respiratory syndrome (SARS-CoV-2), the etiological agent of COVID-19 disease, the progression from acute respiratory failure to sepsis has been correlated with the release of HMGB1." (PMID 35335612, 2022). "Serum and tissue HMGB1 levels rise during infection, particularly in sepsis, and play a crucial role in systemic inflammation." (PMID 36562037, 2022).
Sepsis (continued). "The mRNA expression level of HMGB1 was considerably reduced after 10 days of NC supplementation in patients with sepsis." (PMID 36562037, 2022). "HMGB1 is markedly elevated in human sepsis and is widely known as a late mediator of sepsis, leading to greater morbidity, and mortality." (PMID 35961978, 2022). "Another study discovered that haptoglobin also bound HMGB1 through a CD163-dependent pathway that confers protection against HMGB1-mediated inflammation in sepsis." (PMID 36230933, 2022). "High mobility group box protein 1 (HMGB1) was first discovered as a novel proinflammatory mediator in 1999 in studies of sepsis." (PMID 36465622, 2022). "During sepsis, high concentrations of HMGB-1 stimulate the production of pro-inflammatory cytokines, which are associated with MOD and mortality." (PMID 36562037, 2022). "Blood levels of HMGB1 are correlated not only with the initial severity of the injury but also with the secondary development of sepsis or multiorgan failure, particularly pulmonary and renal." (PMID 36726379, 2022). "We found that CLP sepsis markedly increased HMGB1 levels in serum exosomes compared with sham control." (PMID 34363018, 2022). "lncRNA GAS5 promotes sepsis-induced myocardial depression via the miR-449b/HMGB1 axis and the following NF-κB activation." (PMID 35720285, 2022). "HMGB1 plays an important role in regulating the systemic inflammatory response in infectious diseases, and the serum level of HMGB1 in patients with sepsis is elevated." (PMID 35978950, 2022). "HMGB1 binds with high affinity to different receptors, mediating the immune response to necrosis and immune cell invasion to pathogens, sepsis, and trauma." (PMID 35269471, 2022). "In the response to sepsis, HMGB1 activation induced cell death, whereas Rg4 treatment enhanced cell survival by increasing PI3K/p-AKT expression." (PMID 36142743, 2022). "circR-TLK1 sponges miR-17-5p to aggravate mtDNA oxidative damage, mitochondrial dysfunction and cardiomyocyte apoptosis via activating PARP1/HMGB1 axis during sepsis." (PMID 35720285, 2022). "aloin reduces HMGB1 release and sepsis-related mortality by activating SIRT1 and PI3K/Nrf2/HO-1 signals." (PMID 35720285, 2022). "With the deepening of research, drugs for the targeted inhibition of HMGB1 in sepsis have been issued, including painkillers, anti-diabetic drugs and anesthetics." (PMID 35720285, 2022). "Similar findings were observed in a case-control study comparing admission levels of HMGB-1 in patients with MAP or SAP with a sepsis group and healthy controls." (PMID 36713404, 2022). "Previous reports showed that HMGB1 was significantly increased during sepsis in different brain regions, including the hippocampus." (PMID 36552192, 2022). "mung bean coat extract has protective effect against lethal sepsis possibly by stimulating autophagic HMGB1 degradation." (PMID 35720285, 2022). "High mobility group box 1 (HMGB1), a late mediator of lethal systemic inflammation, can trigger sepsis when it leaks into the bloodstream." (PMID 36712689, 2022). "HMGB1 is quickly released into the circulation in severe mechanical trauma, related conditions and sepsis." (PMID 35765707, 2022). "indoprofen exerts a potent therapeutic effect against sepsis by alleviating HMGB1-mediated inflammatory responses." (PMID 35720285, 2022). "The proinflammatory activity of HMGB1 was first discovered in studies of sepsis, and subsequently, the importance of HMGB1 as a proinflammatory cytokine has been demonstrated in many inflammation‐associated diseases." (PMID 34953035, 2022). "In the late stage of sepsis, macrophages will release high mobility group protein B1 (HMGB1), which can stimulate the expression of Sesn2 in DCs." (PMID 35619718, 2022). "reduning injection protects against sepsis partly via inhibition of HMGB1/TLR4/NF-κB/MAPKs signaling pathways." (PMID 35720285, 2022).
Sepsis (continued). "Some studies demonstrated that hepatocyte-released HMGB1 played a vital role in mediating caspase-11-dependent pyroptosis and sepsis lethality." (PMID 36467039, 2022). "Previous research found that HMGB1 plays a critical role in inducing sepsis in humanized mice, most likely by inducing a human cytokine storm, and silencing HMGB1 after the development of symptoms can reverse sepsis in humanized mice." (PMID 35547731, 2022). "13-ethylberberine (13-EBR) promoted the activation of AMPK and p38/MAPK to inhibit HMGB1, whose excessive accumulation leds to fatal endotoxemia and sepsis." (PMID 36147356, 2022). "These authors relate studies showing that circulating concentrations of HMGB-1 are increased during severe clinical sepsis and septic shock and several hours after the peripheral administration of high doses of LPS to rodents." (PMID 35215252, 2022). "circR-PTK2-miR-181c-5p-HMGB1: a new regulatory pathway for microglia activation and hippocampal neuronal apoptosis induced by sepsis." (PMID 35720285, 2022). "In the in vitro and in vivo model of sepsis, the up and down molecules of the IL-17 signaling pathway (HMGB1, RAGE, IL-17A, NK-κB) and inflammatory factors (IL-1β, IL-18) were upregulated." (PMID 36406124, 2022). "Elevated HMGB-1 levels have been demonstrated in several inflammatory syndromes including sepsis, acute myocardial infarction and rheumatoid arthritis, and in this context is postulated to function as a pro-inflammatory mediator." (PMID 36713404, 2022). "The translocation of HMGB1 between cellular compartments is a dynamic process triggered by variety of cell stresses and diseases (sepsis, trauma, hemorrhagic shock, ischemia, etc.)." (PMID 35053249, 2022). "HMGB1 is involved in the development of the systemic inflammatory response and plays a key role in the progression of sepsis." (PMID 35871689, 2022). "The studies of sepsis and HMGs in necroptosis mainly focus on HMGB1, while the studies of other HMGs in necroptosis are still few at present." (PMID 35720285, 2022). "Disruption of the JAK-STAT signaling pathway inhibits HMGB1 release, thereby playing a protective role in sepsis and ischemia/reperfusion injury models." (PMID 35217834, 2022). "In our study, an early release of TNF-α at 6 h was noted, while the time-dependent kinetics of other detected biomarkers (IL-10, bET and HMGB1) were consistent with sepsis progression." (PMID 35615093, 2022). "It attenuates sepsis-induced ALI through HMGB1-RAGE pathways, and reduces LPS-induced HMGB1 through the activation of the Nrf2/HO-1 pathway and NF-κB suppression." (PMID 35720285, 2022). "lncR-HOTAIR is up-regulated in sepsis-induced kidney injury, which promotes HK-2 cell apoptosis in kidney injury through the miR-22/HMGB1 pathway." (PMID 35720285, 2022). "In patients with severe sepsis, there was a direct correlation between HMGB-1 and sRAGE levels, whereas the relationship was inverse in the AP patients." (PMID 36713404, 2022). "Our group previously reported that glucan phosphate improved cardiac function and suppressed HMGB1 translocation to the cytoplasm during sepsis." (PMID 35401579, 2022). "In conclusion, the present study provides a novel mechanistic basis for the deleterious effects of lactate during sepsis through promoting HMGB1 release." (PMID 34363018, 2022). "reduction of HMGB1’s release and septic mortality by biapenem indicate a possibility of successful repositioning of biapenem for the treatment of sepsis." (PMID 35720285, 2022). "The release of HMGB1 into the extracellular matrix can be induced by various cell stresses and diseases such as trauma, hemorrhagic shock, and sepsis." (PMID 35559340, 2022). "In contrast, suppressed lactate production by sodium oxamate, a specific LDH inhibitor, significantly attenuated CLP sepsis-increased serum levels of HMGB1 and lactate, leading to improved survival outcome of septic mice." (PMID 34363018, 2022).
Sepsis (continued). "Toddalolactone protectes LPS-induced sepsis and attenuates LPS-induced inflammatory response by modulating HMGB1-NF-κB translocation." (PMID 35720285, 2022). "glucan phosphate attenuates HMGB1 release from rat myocardial H9C2 cells in LPS-induced sepsis by inhibiting the activation of NF-κB." (PMID 35720285, 2022). "Compared with WT mice, CD19hiFcγRIIbhi B cells from Hmgb1(C106A) mice significantly reduced the survival of mice with sepsis." (PMID 35983056, 2022). "Nuclear-to-cytoplasmic HMGB1 translocation is increased in acute lung injury, and in this context, inhibiting HMGB1 secretion improves sepsis-induced organ injury and systemic inflammatory response syndrome." (PMID 36081910, 2022). "circR TLK1 contributes to sepsis-associated AKI by regulating inflammation and oxidative stress through the miR-106a-5p/HMGB1 axis." (PMID 35720285, 2022). "HMGB1, which is also called a death mediator, is elevated in cases of severe illness including sepsis." (PMID 37234401, 2022). "High mobility group box 1 protein (HMGB1), as a late pro-inflammatory factor, is significantly increased during sepsis in different brain regions, including the hippocampus." (PMID 36552192, 2022). "In contrast, inhibition of lactate production by oxamate significantly suppressed sepsis-increased exosomal HMGB1 production." (PMID 34363018, 2022). "High-mobility group box-1 (HMGB-1) is a DNA-binding nuclear protein that acts as a proinflammatory cytokine, which plays an important role in infections, injury, and sepsis-related inflammation." (PMID 35684514, 2022). "Human macrophage and dendritic cell-specific silencing of HMGB1 ameliorates sepsis in a humanized mice model." (PMID 35720285, 2022). "It stimulates the LC3 structure, as well as inhibits the LPS-induced increase of HMGB1 in autophagy and apoptosis manner acting as a negative regulator of HMGB1 in sepsis." (PMID 35681439, 2022). "HMGB1 serves as a signalling molecule involved in acute and chronic inflammation, for example, in sepsis and arthritis." (PMID 34953035, 2022). "Quercetin exerts protective effects in a sepsis rat model by quenching ROS, activating of the enzymic antioxidant system, and reducing HMGB1 expression." (PMID 35720285, 2022). "Another study indicates that lnc‐GAS5 aggravates myocardial depression in mice with sepsis via the microRNA‐449b/HMGB1 axis and the NF‐κB signaling pathway." (PMID 35325494, 2022). "In acute liver failure, high-mobility group protein-1 (HMGB1) translocation from the nucleus to the cytoplasm increases and inhibition of HMGB1 secretion alleviate systemic inflammatory response syndrome and sepsis-induced organ damage." (PMID 35222035, 2022). "Extracellular HMGB1 carries the characteristic alarm protein functions to activate innate immunity, and HMGB1 can be actively or passively released after cell death during endotoxemia or sepsis." (PMID 36189354, 2022). "In the studies about HMGs and non-coding RNAs in sepsis, many miRNA/lncRNA and few circRNA participate in the mechanism of sepsis by targeting HMGs, especially HMGB1." (PMID 35720285, 2022). "Overexpressed miR-129-5p attenuates acute lung injury induced by sepsis through targeted downregulation of HMGB1." (PMID 36274974, 2022). "More importantly, they found that HMGB1 and caspase-11 was upregulated 24 hours after the onset of sepsis, providing the basis for targeted therapy for sepsis." (PMID 35572571, 2022). "Rosmarinic acid suppressed CLP-or LPS-stimulated HMGB1 release, and inhibited HMGB1 mediated inflammation in endothelial cells and sepsis-related mortality." (PMID 35684514, 2022). "toddalolactone protects LPS-induced sepsis and attenuates LPS-induced inflammatory response by modulating HMGB1-NF-κB translocation." (PMID 35720285, 2022). "High circulating levels of lactate and high mobility group box-1 (HMGB1) are associated with the severity and mortality of sepsis." (PMID 34363018, 2022).